TNFRSF11B (TNF receptor superfamily member 11b)
Description:
Acts as a decoy receptor for TNFSF11/RANKL and thereby neutralizes its function in osteoclastogenesis. Inhibits the activation of osteoclasts and promotes osteoclast apoptosis in vitro. Bone homeostasis seems to depend on the local ratio between TNFSF11 and TNFRSF11B. May also play a role in preventing arterial calcification. May act as decoy receptor for TNFSF10/TRAIL and protect against apoptosis. TNFSF10/TRAIL binding blocks the inhibition of osteoclastogenesis.
Synonyms: OCIF; OPG; TR1; PDB5
Tractability: Antibody: its Gene Ontology location is reachable by antibodies, with high confidence; UniProt places it where antibodies can reach, with medium confidence; UniProt predicts a signal peptide or a membrane-spanning region.
Safety:
Unwanted effects reported when the protein is acted on. In parentheses: how it was acted on, where the effect was seen, and who reports it.
aromatase inhibitor-associated musculoskeletal syndrome, metabolic bone disease, or osteoporosis (source: ClinPGx)
Gene: Protein-coding gene on chromosome 8 (118,923,557 to 118,952,055, reverse strand). Ensembl gene ENSG00000164761.
Subcellular location: Secreted
Subcellular location (Human Protein Atlas): Golgi apparatus; Nucleoli; Nucleoplasm; Predicted to be secreted
Pathways (Reactome):
Immune System: TNFs bind their physiological receptors
Gene Ontology:
Molecular function: protein binding; cytokine activity; signaling receptor activity; heparan sulfate binding
Biological process: signal transduction; skeletal system development
Cellular component: extracellular region; receptor complex; plasma membrane; extracellular matrix
Genetic constraint (gnomAD): Loss-of-function variants: 16 observed, 44.78 expected, observed/expected ratio (o/e) 0.36, 90% interval 0.24 to 0.54. The upper end of that interval is the gene's LOEUF score, 0.54, which puts it in group 2 of 6, group 1 being the genes least tolerant of losing a copy. Missense variants: 444 observed, 513.51 expected, observed/expected ratio (o/e) 0.86, 90% interval 0.8 to 0.94. Synonymous variants: 185 observed, 190.09 expected, observed/expected ratio (o/e) 0.97, 90% interval 0.86 to 1.1.
Homologues: Orthologues: chimpanzee TNFRSF11B (99% identical), macaque TNFRSF11B (97% identical), dog TNFRSF11B (92% identical), pig TNFRSF11B (91% identical), rabbit TNFRSF11B (89% identical), guinea pig TNFRSF11B (89% identical), mouse Tnfrsf11b (86% identical), rat Tnfrsf11b (85% identical), tropical clawed frog tnfrsf11b (44% identical). Paralogues in human: TNFRSF6B (22% identical), TNFRSF21 (21% identical), TNFRSF11A (19% identical), TNFRSF1B (17% identical), TNFRSF1A (16% identical), NGFR (16% identical), CD40 (15% identical), LTBR (15% identical), TNFRSF8 (14% identical), TNFRSF14 (14% identical), RELT (13% identical), TNFRSF9 (13% identical), and 9 more.
Diseases named in the same sentence as TNFRSF11B in open-access papers:
TNFRSF11B is named in the same sentence as 97 diseases in open-access papers, as found by Europe PMC text mining. Sharing a sentence is not in itself a finding about the gene and the disease. The quoted sentences say what the papers report.
osteoporosis (17 papers, 2010 to 2025). A condition of reduced bone mass, with decreased cortical thickness and a decrease in the number and size of the trabeculae of cancellous bone (but normal chemical composition), resulting in increased fracture incidence. "Analysis of the rs2073617 variant of the TNFRSF11B gene with the risk of osteoporosis indicates that in the adjusted model, the heterozygous TC genotype increases the risk by 30%, and the CC genotype by 78%, compared to the homozygous TT genotype (p = 0.155)." (PMID 41009461, 2025). "Associations of TNFRSF11B gene haplotypes with osteopenia and osteoporosis were carried out for four polymorphic variants." (PMID 38137439, 2023). "Comparing the allele frequency of the TNFRSF11B gene variants studied in the control and osteoporosis groups, a statistically significant difference was observed for rs2073617." (PMID 38137439, 2023). "In this study, we evaluated the association of three TNFRSF11B promoter polymorphisms with presence of osteoporosis in RA." (PMID 26065000, 2015). "Different studies have been able to identify single nucleotide polymorphisms (SNPs) in TNFSF11 (RANKL) and TNFRSF11B (OPG) genes in association with osteoporosis or low bone density." (PMID 26065000, 2015). "The aim of this study was to analyze the selected single-nucleotide polymorphisms (SNPs) of the OPG (TNFRSF11B) gene, rs3102735 (−163A>G), rs3134070 (−245T>G), rs207361 (−950T>C), rs7844539 (6890A>C), and rs2073618 (1181G>C), in the development of osteoporosis and osteopenia in postmenopausal women." (PMID 38137439, 2023). "Also, in the association analysis of polymorphic variants of the TNFRSF11B gene with osteoporosis risk, the most interesting results were obtained for rs2073617." (PMID 38137439, 2023). "A study in European population (Eslovenia) showed that two SNPs named rs3134069 and rs3134070 in the TNFRSF11B could form a haplotype with susceptibility to osteoporosis." (PMID 26065000, 2015). "The rs2073617 polymorphism (TNFRSF11B promoter region) influences osteoprotegerin expression and has been linked to BMD variability and osteoporosis risk in meta-analyses." (PMID 41009461, 2025). "Several large GWAS have investigated the genetics of osteoporosis, revealing BMD-associated genes, including ESR1, LRP4, ITGA1, LRP5, SOST, SPP1, TNFRSF11A (RANK), TNFRSF11 (RANKL), and TNFRSF11B (OPG)." (PMID 39769358, 2024). "Osteoprotegerin (OPG) encoded by the TNFRSF11B gene antagonizes RANKL and inhibits osteoclastogenesis and has been demonstrated to significantly alleviate osteoporosis." (PMID 34145772, 2022). "The previous pathologic studies found that SNPs in 5′ UTR region can lead to abnormal expression of osteoporosis-related genes, including TNFRSF11B and CYP17." (PMID 32269995, 2020). "The TNF receptor family is involved in many of the selected inflammatory diseases, e.g., TNFRSF10B in Osteoporosis, Osteomyelitis and periodontitis, TNFRSF11B and TNFSF13B in Osteopetrosis and Periodontitis, and TNFIP6/8 in Osteomyelitis." (PMID 30497370, 2018). "Because bone loss is accelerated by OCLs, the previous finding that therapeutic potentials of TMs on osteoporosis prompted us to investigate the correlation of TNFRSF11B expression and inhibitory activity of OPG on OCLs differentiation." (PMID 29214990, 2017). "Our results did not allow determining an unequivocal association between the polymorphic variants of the TNFRSF11B 5′UTR region and a susceptibility to osteoporosis in IBD patients." (PMID 27639566, 2016). "In addition, three SNPs near the TNFRSF11B gene were associated with decreased BMD and increased risk of osteoporosis." (PMID 39337893, 2024). "Tnfrsf11b (OPG) knockout mice have osteoporosis as a result of uncontrolled osteoclasts." (PMID 34957116, 2021).
osteoporosis (continued). "Compared to GWAS-identified candidate genes that do not show differential expression in these cellular models, genes like TNFRSF11B/OPG with differential expression are more likely to be involved in skeletal metabolism and thus more likely to be truly associated with osteoporosis." (PMID 20548944, 2010). "Additionally, analysis of the TNFRSF11B rs2073617 variant did not demonstrate statistical significance in the risk of osteoporosis." (PMID 41009461, 2025). "TNFRSF11B, LRP5, RUNX2, SP7, SOST, DKKI, and ESR1 have a strong influence on osteoporosis development, according to GWAS data." (PMID 37958752, 2023). "The study aimed to evaluate the association between C209T (rs3134069), T295G (rs3134070), SNPs C950T (rs2073617) in the TNFRSF11B (OPG) gene, and osteoporosis in RA." (PMID 34603889, 2021). "We aim to evaluate the association between SNPs C950T (rs2073617), C209T (rs3134069), T245G (rs3134070) in the TNFRSF11B (OPG) gene, and osteoporosis in RA." (PMID 26065000, 2015). "Therefore, the aim of the present study was to assess if there is an association between SNPs C950T (rs2073617), C2097 (rs3134069), and T245G (rs3134070) in the TNFRSF11B (OPG) gene and osteoporosis in rheumatoid arthritis patients." (PMID 26065000, 2015). "In conclusion, we confirmed the association of C allele of the C950T SNP in the TNFRSF11B gene with RA patients, but we were not able to support our main hypothesis that this polymorphism in the OPG gene is associated with osteoporosis in RA." (PMID 26065000, 2015).
breast cancer (8 papers, 2010 to 2026). A primary or metastatic malignant neoplasm involving the breast. "This review investigates the role of osteoprotegerin (OPG) in the pathogenesis of breast cancer, with a focus on understanding the effects of the RANKL/RANK/OPG pathway and single nucleotide polymorphisms (SNPs) in the OPG-encoding gene (TNFRSF11B)." (PMID 39941709, 2025). "With exception of VANGL2, up-regulation of the genes involved in Wnt signaling pathway, namely WNT5A, MSX2, TCF7L2 and TNFRSF11B, was confirmed in the validation set, further emphasizing the important role of the Wnt signaling pathway in PIK3CA-mutated breast cancer." (PMID 21209903, 2010).
atherosclerosis (7 papers, 2008 to 2025). A disease characterized by the build-up of fatty material and calcium deposition in the arterial wall resulting in partial or complete occlusion of the arterial lumen. "Elevated TNFRSF11B levels have been associated with arterial stiffness, vascular calcification, and an increased risk of cardiovascular events, potentially reflecting maladaptive remodeling in atherosclerosis." (PMID 40801988, 2025). "With regard to the vitreal proteins detected in CRVO patients, TNFRSF11B is a marker of atherosclerosis, though its pathophysiological role is yet unclear." (PMID 25978399, 2015). "Recent studies on TNFRSF11B tissue expression, serum levels, or gene polymorphisms also suggest an important role of the RANKL/RANK/TNFRSF11B cytokine system in atherosclerosis and vascular calcification." (PMID 19424482, 2008). "An unannotated disease-specific cell cluster (A-cluster 6) co-expressed contractile VSMC markers (Myh11, Acta2, and Cnn1) with several atherosclerosis-induced ECM genes (Col1a1, Mgp, Eln, Fn1, Col4a1, and Col8a1) and had reduced levels of Ly6a, Vcam1, and Tnfrsf11b compared to imVSMCs." (PMID 40577585, 2025). "TNFRSF11B was positively correlated with the expression of intercellular adhesion molecule 1 (ICAM1), and increased the infiltration of monocytes into subendothelial spaces to promote atherosclerosis." (PMID 38333413, 2024).
gastric cancer (7 papers, 2020 to 2025). A primary or metastatic malignant neoplasm involving the stomach. "Given that some of the upregulated hub genes in our study, such as SAA1 and TNFRSF11B, are involved in inflammatory and immune-related pathways, targeting them with zoledronic acid may provide a repurposing opportunity to disrupt tumor-supportive signaling in H. pylori–associated gastric cancer." (PMID 40445003, 2025). "TNFRSF11B activation of the Wnt/β-catenin signaling pathway has been found to promote the progression of gastric cancer." (PMID 37713112, 2024). "In immunohistochemistry assay, we detected that the expression of TNFRSF11B was upregulated in gastric cancer." (PMID 32398963, 2020). "Our research systematically assessed the effects of TNFRSF11B in gastric cancer and found the novel regulation of the GSK3β/β-catenin pathway through TNFRSF11B." (PMID 32398963, 2020). "TNFRSF11B was rarely expressed in the normal gastric mucosa, but was highly expressed in the cytoplasm of gastric cancer tissues." (PMID 32398963, 2020). "In gastric cancer, high expression of TNFRSF11B was found in gastric cancer cell lines, primary cancer and bone metastasis tissues." (PMID 32398963, 2020). "The expression of TNFRSF11B was analyzed from the Cancer Genome Atlas (TCGA) project gastric cancer database and Oncomine database." (PMID 32398963, 2020). "In order to clarify the role of TNFRSF11B in the pathogenesis of gastric cancer, we analyzed the relationship between the expression of TNFRSF11B and the clinicopathological characteristics of GC patients." (PMID 32398963, 2020). "In the present study, we found that the expression of TNFRSF11B was higher in gastric cancer tissues compared to normal tissues from the TCGA and Oncomine databases." (PMID 32398963, 2020). "Moreover, TNFRSF11B can also activate Wnt/β-catenin signaling and promote gastric cancer progression." (PMID 39119088, 2024). "Tnfrsf11b can activate the Wnt/β‐catenin signaling pathway to promote gastric cancer progression." (PMID 37666495, 2024). "Overall, we found that the expression of TNFRSF11B was higher in all of the gastric cancer tissues compared with normal tissues, suggesting that TNFRSF11B may be a crucial factor in gastric cancer." (PMID 32398963, 2020). "These researches suggest that TNFRSF11B may have potential as a biomarker and clinical target in gastric cancer, warranting further study into the biological role of TNFRSF11B in gastric cancer." (PMID 32398963, 2020). "The expression rate of TNFRSF11B in gastric cancer tissues was 74.3% (52/70)." (PMID 32398963, 2020). "The expression of TNFRSF11B was measured by immunohistochemistry (IHC) in gastric cancer tissues." (PMID 32398963, 2020). "To elucidate the role of TNFRSF11B in the carcinogenesis of gastric cancer, we analyzed the relationship between TNFRSF11B expression and the clinicopathological characteristics of gastric cancer patients.The frequency of TNFRSF11B expression increased remarkably with the progression of TNM stage." (PMID 32398963, 2020). "Next, we researched the downstream effectors of TNFRSF11B in gastric cancer." (PMID 32398963, 2020). "In our study, we aimed to clarify the molecular roles of TNFRSF11B in gastric cancer." (PMID 32398963, 2020). "However, there are no studies for the biological function and molecular mechanism of TNFRSF11B in gastric cancer." (PMID 32398963, 2020). "We suggested that TNFRSF11B is potentially useful as a prognostic biomarker and could be a novel therapeutic target for gastric cancer." (PMID 32398963, 2020). "However, little is unveiled regarding the complex mechanisms of TNFRSF11B in human gastric cancer (GC)." (PMID 32398963, 2020). "Meanwhile, TNFRSF11B activated the phosphorylation of GSK-3β and enhanced the expression of β-catenin and its downstream effectors to strengthen the invasiveness of gastric cancer." (PMID 34938284, 2021).
gastric cancer (continued). "Multivariate Cox regression showed that there was not enough evidence to suggest the TNFRSF11B expression was an independent factor for the prognosis of gastric cancer patients." (PMID 32398963, 2020).
colon carcinoma (6 papers, 2018 to 2025). "TNFRSF11B is associated with advanced lymph node metastasis and poorer survival outcomes in colon cancer patients, potentially by inhibiting memory-activated CD4+ T cell infiltration." (PMID 40901678, 2025). "We analyzed the relationship between the survival-related IRGs and the characteristics of colon cancer patients and found that only TNFRSF11B was strongly associated with TNM stage and lymph node status." (PMID 34938284, 2021). "In our cohort, 72.09% (62/86) of the colon cancer patients who received radical surgery had TNFRSF11B overexpression, which was associated with significantly shorter overall survival times (p = 0.072)." (PMID 34938284, 2021). "We hypothesized that the expression of TNFRSF11B in colon cancer may be regulated by pathogenic E. coli." (PMID 34938284, 2021). "In this study, after analysis of immune-related genes in the Cancer Genome Atlas Colon Adenocarcinoma (TCGA-COAD) dataset, we defined TNFRSF11B as an independent risk factor for the prognosis of colon cancers, which is closely related to tumor stage and lymph node metastasis." (PMID 34938284, 2021). "TNFRSF11B is highly expressed in colon cancer and inhibits the infiltration of memory CD4+ T cells in the colon cancer microenvironment, thereby weakening the immune killing response to cancer cells." (PMID 39119088, 2024). "TNFRSF11B is a prognostic factor in colon cancer and suppresses memory CD4 + T cell infiltration in the colon cancer microenvironment." (PMID 37543576, 2023). "To validate the role of TNFRSF11B in the progression of colon cancer, we used immunohistochemistry (IHC) to assess the expression of TNFRSF11B and its correlation with pathological features." (PMID 34938284, 2021). "Here, we analyzed four independent datasets at the transcriptional and protein levels to determine the role of TNFRSF11B in the tumorigenesis of colon cancer." (PMID 34938284, 2021). "Using the TCGA-COAD dataset (n = 514), we identified TNFRSF11B as a prognostic factor of colon cancer." (PMID 34938284, 2021). "At the protein and transcriptional levels, we attempted to illuminate the role of TNFRSF11B in the regulation of the colon cancer immune microenvironment." (PMID 34938284, 2021). "Increased expression of TNFRSF11B significantly enhanced three cancer-related functional states, namely, metastasis, angiogenesis and inflammation, in colon cancer cells (cor = 0.360, cor = 0.224, and cor = 0283, respectively, all p values <0.001)." (PMID 34938284, 2021). "TNFRSF11B expression was also enriched in the terminal differentiation of colon cancer cells through pseudotime analysis." (PMID 34938284, 2021). "In our cohort, we also demonstrated that TNFRSF11B enhanced colon cancer cell invasion into the lymphovascular system." (PMID 34938284, 2021). "In our IHC dataset, 72.09% (62/86) of the colon cancer patients had TNFRSF11B overexpression with significantly shorter overall survival times (p = 0.072)." (PMID 34938284, 2021). "To analyze the potential role of TNFRSF11B in the regulation of the immune response, we determined the different subsets of immunocytes between different TNFRSF11B-expressing colon cancer tissues in our cohort via CIBERSORT algorithms." (PMID 34938284, 2021). "Using the TIMER 2.0 database, we also demonstrated that TNFRSF11B negatively affected the infiltration of activated memory CD4+ T cells into the colon cancer microenvironment (cor = −0.158, p = 0.008)." (PMID 34938284, 2021). "In our study, we observed the immunosuppressive role of TNFRSF11B in the regulation of memory CD4+ T cell activation in colon cancer tissue and peripheral blood monocytes, and our findings were validated in TCGA-COAD datasets." (PMID 34938284, 2021). "In this study, we explored the mechanism by which TNFRSF11B remodels the colon cancer immune response via bioinformatics analysis and confirmed the results with in vitro experiments; however, more biological experiments are needed to validate our findings." (PMID 34938284, 2021).